IL18 (interleukin 18)
Diseases named in the same sentence as IL18 in open-access papers (continued):
Sharing a sentence is not in itself a finding about the gene and the disease.
Acute hepatitis (3 papers, 2015 to 2025). Acute hepatic injury resulting from inflammation typically accompanied by increased serum alanine transaminase activity. "CA nanoparticles have also demonstrated the ability to reduce inflammation and apoptosis in acute hepatitis models by decreasing levels of TNF-α, IL-1β, and IL-18, as well as inhibiting NF-κB, NLRP3, and caspase-1, while promoting Bcl-2 levels." (PMID 40869259, 2025). "While not specific to the liver, IL-18 expression is known to be enhanced in acute hepatic diseases such as fulminant hepatic failure and acute hepatitis." (PMID 27867357, 2016).
adenoma (3 papers, 2022 to 2025). A neoplasm arising from the epithelium. "For example, we have demonstrated that the levels of interferon (IFN)-γ, IL-12A and IL-18 were increased in adenoma tissues and decreased in CRC tissues." (PMID 36466926, 2022). "Since these three cytokines have been recognized as critical factors in maintaining antitumor immunity, the increasing IFN-γ, IL-12 and IL-18 in the TME may imply an initial effort of the host to combat the appearance of adenomas in the colorectal mucosa." (PMID 36466926, 2022). "The enrichment analysis showed a higher abundance of hub genes related to adenoma/adenocarcinoma, malignancy, metastasis, extracellular structure organization, PI3K-Akt signaling pathway, IL-18, cancer pathway, GPCR downstream signaling, and B-cell activation." (PMID 38637796, 2024). "Similarly, our systematic review showed that Th1 cytokines (L-12A, IL-18, IFN-γ, and TNF-α) are upregulated in CR adenomas but turn downwards in CRC tissues." (PMID 40149674, 2025).
alcohol (3 papers, 2018 to 2023). "Alcoholism and smoking induce decreased expression of Interleukin 18 (IL-18) and DDX3 protein, which regulate the cell cycle and progression of malignant neoplasm." (PMID 29680854, 2018). "The results revealed that FMT significantly decreased the levels of TNF-α, IL-4 and IL-18, which indicated that FMT could ameliorate the inflammatory reaction in alcohol dependence mice." (PMID 38249454, 2023).
alexithymia (3 papers, 2019 to 2022). An agnosia that is a deficiency in understanding, processing, or describing emotions. "Furthermore, recent studies have demonstrated an interaction between IL-18 and 5-HT may cause alexithymia." (PMID 35931995, 2022).
alveolitis (3 papers, 2011 to 2019). "Surprisingly, the T-bet-/- mice exhibited decreased alveolitis compared to the WT or IL-18-/- mice during both the early and late stages of the disease." (PMID 21699708, 2011). "The results demonstrate that following exposure, WT and IL-18-/- mice develop similar levels of alveolitis whereas T-bet-/- mice developed a less severe alveolitis." (PMID 21699708, 2011). "However, despite the decrease in IL-17mRNA the level of alveolitis (and neutrophil recruitment) was similar in the IL-18-/- mice compared to WT mice exposed to S. rectivirgula." (PMID 21699708, 2011). "However, despite the decreased alveolitis in T-bet-/- mice, the levels of MIP-2 mRNA, which is strongly induced in HP, was similar to IL-18-/- and WT mice exposed to S. rectivirgula." (PMID 21699708, 2011).
anorexia nervosa (3 papers, 2019 to 2022). A disorder most often seen in adolescent females characterized by a refusal to maintain a minimally normal body weight, an intense fear of gaining weight, a disturbance in body image, and, in postmenarcheal females, the development of amenorrhea. "In humans, plasma IL-18 levels were significantly decreased in patients with anorexia nervosa and circulating IL-18 levels correlated to body mass index (BMI) in controls, but not in anorexic patients." (PMID 36313762, 2022). "Worth mentioning is fact, that one study demonstrated significantly decreased plasma IL-18 levels in patients with anorexia nervosa compared to controls." (PMID 32297262, 2020). "Therefore, decreased levels of IL-18 may commonly occur in patients with chronic anorexia nervosa." (PMID 32297262, 2020). "Plasma IL-18 levels directly correlated with BMI in controls, but not in patients with anorexia nervosa." (PMID 32297262, 2020).
arteriosclerosis (3 papers, 2018 to 2023). A vascular disorder characterized by thickening and hardening of the walls of the arteries. "In conclusion, IL-18 could rise really early in kidney injury which caused by unilateral partial obstruction due to arterial hyalinization, arteriosclerosis, and interstitial inflammation processes." (PMID 37363465, 2023). "The increase of IL-18 is due to arterial hyalinization, arteriosclerosis and interstitial inflammation processes which occurred as early as day 4th after unilateral ureter was partially ligated." (PMID 37363465, 2023).
Ascites (3 papers, 2014 to 2026). Accumulation of fluid in the peritoneal cavity (between the layers of the peritoneum that lines the abdomen). "Levels of both urinary NGAL and urinary IL-18 were significantly higher in patients with ascites and renal impairment compared to the other two groups." (PMID 26361506, 2015). "Patients with renal impairment had higher urinary IL-18 levels (983 ± 594 μg/g creatinine) compared to those of patients without renal impairment, either with or without ascites (296.56 ± 113, 254.5 ± 77.9 μg/g creatinine, resp)." (PMID 24967242, 2014).
autoimmune hepatitis (3 papers, 2015 to 2023). Hepatitis caused by autoantibodies. "The authors hypothesized that cytokine driven (IL-12 and IL-18) activation could lead to cell death and peripheral loss of MAIT cells, like other inflammatory conditions including autoimmune hepatitis." (PMID 37877022, 2023). "Autoimmune hepatitis with a serum IL‐18 concentration of 571.62; 502.47–730.31 pg/mL was not significantly different from the healthy controls (p > 0.05)." (PMID 33720453, 2021). "The IL‐18 concentration in patients with autoimmune hepatitis did not increase significantly (p > 0.05)." (PMID 33720453, 2021).
autoimmune thyroid disease (3 papers, 2018 to 2024). Inflammatory disease of the thyroid gland due to autoimmune responses leading to lymphocytic infiltration of the gland. "Inflammasomes, which mediate the maturation of interleukin-1β (IL-1β) and interleukin-18 (IL-18), are of fundamental importance in autoimmune thyroid diseases (AIT)." (PMID 38999993, 2024). "Correlation between NLRP3, NLRP1, NLRC4, absent in melanoma 2 (AIM2), ASC, caspase-1, IL-1β, and IL-18 expression in the autoimmune thyroiditis group." (PMID 29915579, 2018).
breast invasive carcinoma (3 papers, 2019 to 2024). "Another study indicated that the inhibition of the NLRP3 inflammasome stimulated the recruitment and activation of Natural Killer cells in invasive breast cancer model, independently of IL-1β and IL-18 signaling." (PMID 39433537, 2024). "We aimed to explore the effect of YAP1 in tumor aggressiveness and immune evasion in breast invasive carcinoma and metastatic breast cancer in the context of Interleukin‐18 (IL‐18) in silico." (PMID 34196131, 2022). "In conclusion, the present data analysis suggests that IL‐18 might influence YAP1 in Breast oncogenesis through the production of IFNG and IL‐18 expression is positively correlated with YAP1 expression in breast invasive carcinoma." (PMID 34196131, 2022). "Taken together, the present data provide crucial clinically significant information that IL‐18 expression might become an important prognostic feature in YAP1 overexpressed breast invasive carcinoma and can be considered as a potential target for tumor treatment." (PMID 34196131, 2022). "Our finding also exhibited a positive correlation between IL‐18 and YAP1 via IFNG gene expression and showed that IL‐18 expression is positively correlated with YAP1 in breast invasive carcinoma." (PMID 34196131, 2022). "In addition, the overall oncoprint of YAP1, IL‐18 and IFNG gene expressions in Breast Invasive Carcinoma (PanCancer Atlas) cohort showed that mRNA expression was up‐regulated by 3.02, 2.82, and 3.22% (YAP1, IL18 and IFNG) in all patients, respectively." (PMID 34196131, 2022).
bronchiolitis (3 papers, 2019 to 2024). Inflammation of the bronchioles characterized by swelling of the bronchioles and mucus accumulation. "Elevated levels of IL-18 were identified in bronchiolitis, recurrent tonsillitis, refractory Mycoplasma pneumianiae, and in patients with SARS-CoV-2 infection." (PMID 39431236, 2024). "Pro-inflammatory cytokines IL1β, IL6, TNFα, IL18 and IL23 were increased in the bronchiolitis samples relative to their respective control cohort." (PMID 36561744, 2022). "Here we show that elevated levels of pro-inflammatory cytokines (IL1β, IL6, TNFα, IL18, IL23), regulatory cytokines (IL10, IL17A) and IFNγ were found in the three bronchiolitis cohorts." (PMID 36561744, 2022).
campylobacteriosis (3 papers, 2016 to 2017). Infections with bacteria of the genus campylobacter. "In conclusion, the regulatory pathways within the IL-23/IL-22/IL-18 axis following C. jejuni infection need to be further unraveled in future studies in order to improve our understanding of the distinct molecular mechanisms underlying campylobacteriosis." (PMID 27385977, 2016). "Very recently our group has highlighted the importance of the IL-23/IL-22/IL-18 axis in campylobacteriosis." (PMID 28127403, 2017). "In the present study we dissected the role of cytokines belonging to the IL-23 / IL-22 / IL-18 axis in murine campylobacteriosis." (PMID 27322540, 2016).
cerebral malaria (3 papers, 2013 to 2019). A sequestration of Plasmodium falciparum in the brain, which can cause coma and/or seizures. "Studies in mice indicate that the inflammatory response to Plasmodium infection and the host susceptibility to experimental cerebral malaria are independent of Nlrp3 inflammasome-dependent caspase-1 activation of IL-1β and IL-18." (PMID 23405174, 2013). "While Dostert and colleagues demonstrated a partial protection to experimental cerebral malaria in NLRP3−/− mice, other studies reported that this pathological process occurs independent of NLRP3, ASC, Caspase-1, IL-1R, IL-1β, and IL-18." (PMID 24453977, 2014).
cerebrovascular disease (3 papers, 2018 to 2024). "A network of inflammatory molecules driven by IL-18 is associated with overt and antecedent white matter injury resulting from cerebrovascular disease and may be a promising peripheral biomarker for vascular white matter injury." (PMID 31978079, 2020). "Our findings suggest that an IL-18-centered network of systemic inflammation is associated with overt and antecedent white matter injury resulting from cerebrovascular disease and may be a promising biomarker of cSVD." (PMID 31978079, 2020). "Finally, high IL-18 levels may be strongly associated with the development of cerebrovascular disease through their association with cardiovascular risk factors." (PMID 39247699, 2024). "In the future, IL-18 may be included in the progression of preventive therapies to reduce the incidence of cerebrovascular diseases." (PMID 29485097, 2018).
Chagas cardiomyopathy (3 papers, 2019 to 2024). A disease of the cardiac muscle developed subsequent to the initial protozoan infection by trypanosoma cruzi. "Meta-analysis of IL18 variants, Latin American cohorts for Chagas cardiomyopathy susceptibility." (PMID 31751351, 2019). "Our data strengthens the potential benefit of targeting IL18 as a therapy in Chagas cardiomyopathy." (PMID 33193300, 2020).
chorioamnionitis (3 papers, 2018 to 2025). A morphologic finding indicating inflammation of the fetal sac membranes. "In contrast, targeted analysis of IL8, IL10, IL18, TNFα in maternal plasma of the 2 d Sterile Chorioamnionitis Group animals improved predictive value with a mean AUC of 0.73 (95% CI 0.39–1) Sensitivity 100%, Specificity 71%, PPV 0.82, NPV 1.0." (PMID 40464837, 2025). "A further limitation was that we were unable to assay other inflammatory proteins that are generally considered to be the most relevant in intra-amniotic infections, such as IL-1β, IL-10, IL-18, and MMPs, because of limited research funding available." (PMID 29979758, 2018). "We then studied other pro-inflammatory cytokines that are involved in GBS infection and chorioamnionitis, namely IL-18, IL-6 and TNF-α, to evaluate whether they presented the same sexually dichotomous profile." (PMID 31197179, 2019). "We performed targeted analyses utilising Random Forest Algorithm of the same eight cfRNA targets (IL1α, IL1β, IL6, IL8, IL10, IL18, CD14, TNFα) used in the chorioamnionitis study." (PMID 40464837, 2025). "Compared to Negative Control Group animals, the 2 d Sterile Chorioamnionitis Group animals had significantly increased placental mRNA for IL6 (mean dCt difference = 2.77; 95% CI 5.01 to 0.0.53, p = 0.015) and IL18 (mean dCt difference = 1.79; 95% CI 3.28 to 0.29, p = 0.019)." (PMID 40464837, 2025).
contact dermatitis (3 papers, 2020 to 2024). An inflammatory skin condition caused by direct contact between the skin and either an irritating substance or an allergen. "In 2009, there was a case report about irritant contact dermatitis caused by a methylrosaniline patch at the therapeutic concentration of 0.5%; this percentage is close to the 12.5 μM concentration which we observed a significant IL-18 elevation, but not IL-1α." (PMID 32154236, 2020). "Corneocyte concentrations of the inflammasome‐mediated cytokines IL‐1β and IL‐18 in treated skin lesions (disulfiram 5%, mometasone 0.1% or vehicle) of SDS‐induced irritant contact dermatitis were assessed by tape stripping and ELISA 48 h after application of SDS." (PMID 34322217, 2021).
coronary atherosclerosis (3 papers, 2010 to 2021). Atherosclerosis of the coronary vasculature. "Thus, it is suggested that IL-18 possibly causes LV dysfunction indirectly by aggravating coronary atherosclerosis or directly by acting on cardiomyocytes to induce myocardial dysfunction." (PMID 24599060, 2014). "It is speculated that IL-18 may cause LV dysfunction indirectly by aggravating coronary atherosclerosis or directly by acting on cardiomyocytes to induce myocardial remodeling." (PMID 24599060, 2014).
cryptococcal infection (3 papers, 2018 to 2022). "While most studies have shown that IL-18 is important during cryptococcosis, IL-1β itself is sometimes depicted as unnecessary for host protection." (PMID 33380899, 2020).
Encephalopathy (3 papers, 2015 to 2024). Encephalopathy is a term that means brain disease, damage, or malfunction. "The findings suggested that inflammatory factors, such as IL‐1β, IL‐18 and TNF‐α, play an important role in the pathogenesis of encephalopathies." (PMID 38683122, 2024). "Previous literatures have revealed that IL-6 and IL-1β showed significant correlations with PHES score and correlate with health-related quality of life irrespective of MHE Serum IL-6 and IL-18 levels are reported to be correlated with the degree of encephalopathy." (PMID 26039496, 2015).
endometrial cancer (3 papers, 2018 to 2025). Primary or metastatic malignant neoplasm involving the endometrium (mucous membrane that lines the endometrial cavity). "Intriguingly, Efp knockdown represses NF-κB-dependent transactivation and transcription of target genes, such as IL6ST and IL18, in endometrial cancer cells." (PMID 30586414, 2018). "In endometrial cancer, the degranulation ability of neutrophils is affected by serum IL-18 levels." (PMID 40943781, 2025). "Taken together, Efp is suggested to promote endometrial cancer by enhancing the signals of NF-κB and its related factors IL6ST and IL18 in addition to downregulation of 14-3-3σ protein, an Efp ubiquitin ligase-substrate." (PMID 30586414, 2018).
falciparum malaria (3 papers, 2012 to 2021). "Our data add the IL-18/IL-18bp axis to the inflammatory pathways that are dysregulated during falciparum malaria." (PMID 34663245, 2021). "Further, clinical studies in children have shown higher IL-18 levels in uncomplicated compared with severe falciparum malaria." (PMID 34663245, 2021). "A significant increase in IL-18 concentration has been observed in the acute and recovery phase of uncomplicated falciparum malaria, and was correlated with disease severity." (PMID 26953797, 2016). "However, few studies, with a relative low number of patients, have examined circulating IL-18 levels in falciparum malaria." (PMID 34663245, 2021). "Our findings suggest that the IL-18 system could be an important mediator in the immune pathogenesis during falciparum malaria, potentially also representing a target for therapy." (PMID 34663245, 2021). "Our findings suggest that the IL-18 system could be an important mediator in the immunopathogenesis during falciparum malaria, potentially also representing a target for therapy." (PMID 34663245, 2021). "Finally, during follow-up 10 patients with falciparum malaria of which 9 were co-infected with HIV died (in-hospital mortality), and these 10 non-survivors had significantly higher IL-18 levels than the 121 survivors (median [25th, 75th percentile] 7.5 [3.4, 10.1] vs. 3.3 [2.0, 5.5] p = 0.016)." (PMID 34663245, 2021).
fibrosarcoma (3 papers, 2011 to 2021). A malignant mesenchymal fibroblastic neoplasm affecting the soft tissue and bone. "IL-18 produced by the tumor induced M1 macrophages in spontaneous fibrosarcoma (NFSA) tumors, cause the destruction of EC's in vitro, and are suspected to result in the necrosis of NFSA tumors in part by enhancing macrophage phagocytosis." (PMID 31293586, 2019). "In line with data emerging from studies on the eye, IL-18 has also been shown to inhibit neovascularisation in murine fibrosarcoma and suppress growth, an anti-angiogenic function that suggests it may have a role in some contexts as a tumor suppressor." (PMID 31293586, 2019).
gastric ulcer (3 papers, 2013 to 2025). An ulcerated lesion in the mucosal surface of the stomach. "Previous research showed that gastric ulcers caused by ethanol intake may trigger and activate the inflammatory system, accompanied by up-regulated levels of pro-inflammatory cytokines, such as TNF-α, IL-6, IL-12, and IL-18." (PMID 40283949, 2025).
hearing loss (3 papers, 2017 to 2023). "In the reverse MR analysis, based on the MR-PRESSO results, rs949800 was excluded from explaining the causal relationship between cisplatin-induced pediatric hearing impairment and IL-18." (PMID 37919361, 2023). "Accordingly, the inhibition of TNF- in a genetic knockout or by a pharmacological inhibitor decreased the expression of the neuroinflammatory genes TNF-, IL1, IL18, and Nod-like receptor protein 3, and prevented microglial activation and tinnitus in mice with noise-induced hearing loss." (PMID 34020590, 2021). "According to recent publications, it has been confirmed that specific Th-1 mediated immunological responses may be associated with sensorineural hearing loss and MD, implying that as a key regulator of Th1 cells, IL18, may also be a specific MD-related gene." (PMID 28787010, 2017).
Helicobacter infection (3 papers, 2012 to 2025). "However, IL-18 has antagonistic or regulatory effects on IL-1 during Helicobacter infection and in certain other models of inflammatory disease." (PMID 23028835, 2012). "GES-1 cells and Helicobacter infection in vivo aggravate the inflammatory response by down-regulating AKT and increasing NF-κB, which induce NLRP3, pro-IL-1β, IL-1β, and IL-18." (PMID 40264171, 2025). "Taken together, our data show that non-haematopoietic cells in the stomach produce IL-18, which plays a protective role against the development of the pre-neoplastic lesions typically observed in chronic Helicobacter infection." (PMID 37365163, 2023).